GAGE12D (G antigen 12D)
Synonyms: GAGE-12B; OTTHUMG00000024145
Tractability: Antibody: the Human Protein Atlas places it where antibodies can reach.
Gene: Protein-coding gene on chromosome X (49,541,733 to 49,549,094, forward strand). Ensembl gene ENSG00000227488.
Subcellular location (Human Protein Atlas): Plasma membrane; Cytosol; Golgi apparatus
Gene Ontology:
Molecular function: protein binding
Homologues: Orthologues: chimpanzee GAGE10 (82% identical). Paralogues in human: GAGE12C (100% identical), GAGE12E (100% identical), GAGE12F (99% identical), GAGE12G (99% identical), GAGE12H (99% identical), GAGE1 (97% identical), GAGE12J (97% identical), GAGE13 (97% identical), GAGE2A (96% identical), GAGE2E (93% identical), GAGE10 (90% identical), PAGE1 (52% identical), and 10 more.
Diseases named in the same sentence as GAGE12D in open-access papers:
GAGE12D is named in the same sentence as 1 disease in open-access papers, as found by Europe PMC text mining. Sharing a sentence is not in itself a finding about the gene and the disease. The quoted sentences say what the papers report.
gastric cancer (1 paper, 2019). A primary or metastatic malignant neoplasm involving the stomach. "Consistent with our findings, in a previous study, GAGE12B (also known as GAGE12D) was reported to mediate gastric cancer metastasis and growth." (PMID 30871606, 2019).